MYOT (myotilin)
Description:
Component of a complex of multiple actin cross-linking proteins. Involved in the control of myofibril assembly and stability at the Z lines in muscle cells.
Synonyms: TTID; LGMD1; LGMD1A; MFM3; TTOD
Tractability: Antibody: UniProt places it where antibodies can reach, with high confidence; its Gene Ontology location is reachable by antibodies, with medium confidence.
Gene: Protein-coding gene on chromosome 5 (137,867,858 to 137,887,851, forward strand). Ensembl gene ENSG00000120729.
Subcellular location: Cell membrane, sarcolemma; Cytoplasm, cytoskeleton; Cytoplasm, myofibril, sarcomere, Z line
Gene Ontology:
Molecular function: alpha-actinin binding; protein binding; axon guidance receptor activity; structural constituent of muscle
Biological process: homophilic cell-cell adhesion; muscle contraction; synapse organization; axon guidance
Cellular component: Z disc; actin cytoskeleton; axon; neuronal cell body; plasma membrane; cytoskeleton; sarcolemma
Genetic constraint (gnomAD): Loss-of-function variants: 27 observed, 40.34 expected, observed/expected ratio (o/e) 0.67, 90% interval 0.49 to 0.92. The upper end of that interval is the gene's LOEUF score, 0.92, which puts it in group 3 of 6, group 1 being the genes least tolerant of losing a copy. Missense variants: 406 observed, 508.72 expected, observed/expected ratio (o/e) 0.8, 90% interval 0.74 to 0.87. Synonymous variants: 179 observed, 178.59 expected, observed/expected ratio (o/e) 1, 90% interval 0.89 to 1.13.
Homologues: Orthologues: chimpanzee MYOT (99% identical), dog MYOT (93% identical), rabbit MYOT (93% identical), rat Myot (91% identical), mouse Myot (89% identical), guinea pig MYOT (85% identical), pig MYOT (76% identical), tropical clawed frog myot (50% identical), zebrafish myot (38% identical), Caenorhabditis elegans unc-22 (20% identical), Drosophila melanogaster bt (17% identical), Caenorhabditis elegans dim-1 (9% identical). Paralogues in human: MYPN (32% identical), PALLD (31% identical), HMCN1 (25% identical), OBSCN (23% identical), SPEG (19% identical), ALPK3 (17% identical), IGFN1 (14% identical), CCDC141 (9% identical), SPEGNB (4% identical).
Diseases named in the same sentence as MYOT in open-access papers:
MYOT is named in the same sentence as 37 diseases in open-access papers, as found by Europe PMC text mining. Sharing a sentence is not in itself a finding about the gene and the disease. The quoted sentences say what the papers report.
myofibrillar myopathy (15 papers, 2009 to 2025). "Mutations in the human myotilin gene are associated with myofibrillar myopathy (MFM), supporting the notion that myotilin is important for proper maintenance, organization, and/or function of the Z-disc." (PMID 33844684, 2021). "We found abnormal aggregations of the intermediate filament desmin, the myofibrillar protein myotilin, and the chaperone alpha-crystallin B, all three mutated in myofibrillar myopathies." (PMID 31455395, 2019). "Desminopathy belongs to a genetically heterogeneous group of disorders named myofibrillar myopathy, caused by mutations in desmin, αB-crystallin, myotilin, Z-band alternatively spliced PDZ-containing protein, filamin, or Bcl-2-associated athanogene." (PMID 30841624, 2019). "Myofibrillar myopathies constitute a rare group of congenital neuromuscular disorders, frequently associated with mutations in Z-disc proteins such as myotilin." (PMID 19878039, 2009). "All five myotilin defects had, therefore, Z-disc alterations, allowing an enhanced diagnostic precision, and this disorder now belongs to the myofibrillar myopathy group." (PMID 19878039, 2009). "The dominant myofibrillar myopathy causing MYOT S95I mutation was reported in one affected individual with myotilinopathy and is the only single-point missense variant located in the exon 2 that lies in the domain necessary for the interaction of the protein with alpha-actinin." (PMID 37511242, 2023). "Myotilinopathies are a subset of myofibrillar myopathies (MFM), characterized by the presence of mutations in the MYOT gene, which encodes the protein myotilin, which is mainly expressed in the Z‐disk of striated muscle." (PMID 39757377, 2025). "MYOT gene mutations can cause slowly progressive and late-onset myofibrillar myopathies, limb-girdle muscular dystrophy type 1A (LGMD 1A), myofibrillar myopathy (MFM), or spheroid body myopathy." (PMID 36776921, 2023). "Mutations in the human myotilin gene (MYOT) cause myotilinopathy that includes three known types of skeletal muscle diseases: limb girdle muscular dystrophy type 1A, myofibrillar myopathy, and spheroid body myopathy." (PMID 20737540, 2010). "Moreover, Myotilin, a FLNC partner at the Z-disc that underlies myofibrillar myopathy, accumulates in the same FLNC-positive fibres in mice and humans." (PMID 37427997, 2023). "Mutations in the MYOT gene with LGMD1A phenotype have been identified in only two unrelated families, but the gene is also mutated in other forms of muscle disease such as myofibrillar myopathy (MFM), spheroid body myopathy, and late onset distal myopathy." (PMID 21798100, 2011). "Mutations in MYOT have been originally associated with different disorders separated according to the clinical and histological findings into three main categories including autosomal dominant limb–girdle muscular dystrophy type 1A (LGMD1A), myofibrillar myopathy (MFM), and spheroid body myopathy." (PMID 37511242, 2023). "However, despite the fact that mutations in the myotilin gene have been implicated in limb girdle muscular dystrophy 1A (LGMD1A), myofibrillar myopathy (MFM), and in a rare condition called spheroid body myopathy (SBM), the function of myotilin in normal muscle physiology remains unclear." (PMID 25071420, 2014).
myotilinopathy (10 papers, 2010 to 2025). "In conclusion, we report here a whole gene MYOT duplication causing late onset myotilinopathy, possibly through a gene dose effect." (PMID 39757377, 2025). "At present, diseases caused by mutations in MYOT are considered as a single entity, namely myotilinopathies (OMIM #609200), characterized by a continuum of phenotypic and pathological manifestations." (PMID 37511242, 2023). "The identification of the ratio of myotilin to filamin C in aggregates as a highly sensitive and specific diagnostic marker for myotilinopathy underlines that proteomic analysis can be useful in differential diagnosis of myofibrillar myopathies." (PMID 26842778, 2016). "MFM associated with myotilin mutations, hereafter referred to as myotilinopathy, usually manifests between the 5th and 8th decade of life with progressive muscle weakness most often starting at distal lower limbs." (PMID 26842778, 2016). "We here present a proteomic study in myotilinopathy, including samples from 15 patients harboring four different MYOT mutations." (PMID 26842778, 2016). "The ratio of the myotilin and filamin C proportions in aggregate samples was identified as a new diagnostic marker for myotilinopathy with a high sensitivity (100 %) and specificity (91 %) in our MFM cohort." (PMID 26842778, 2016). "Among several post-translational modifications, desmin was demonstrated to be a major target of oxidation and nitration in both desminopathies and myotilinopathies, characterized by mutation of desmin and myotilin, respectively." (PMID 26333167, 2015). "We report here the first family of myotilinopathy caused by a duplication of the MYOT gene." (PMID 39757377, 2025). "MYOT mutations mainly manifest in myopathies, which are referred to as “myotilinopathies”." (PMID 36776921, 2023). "This raised the important question whether a combination of toxic gain-of-function and loss-of-function of myotilin is present in myotilinopathy." (PMID 26842778, 2016). "Although the exact pathomechanisms behind myotilinopathies are yet to be completely elucidated, missense variants in MYOT, which typically cause MFM via an accumulation of protein aggregates may be due to an impaired protein degradation system linked to Z-disc structural abnormalities." (PMID 33802723, 2021). "To validate the pathogenicity of this novel MYOT duplication we performed a detailed myopathological analysis of muscle biopsies looking for evidence in support of myotilinopathy." (PMID 39757377, 2025). "In this study, we report a family with a duplication of the whole MYOT gene and late‐onset myotilinopathy." (PMID 39757377, 2025). "Such diseases caused by pathogenic variants in MYOT are present in 10% of MFM patients and have been termed “myotilinopathies”." (PMID 33802723, 2021). "Since myotilin aggregation is common in myotilinopathy (like other MFMs), mouse models have been used to better understand the pathological effect." (PMID 33802723, 2021). "Z-disc streaming is reported in myotilinopathies along with the accumulation of dense myotilin and desmin-containing protein aggregates." (PMID 33802723, 2021). "First, sequence conservation analysis of myotilin shed light on the molecular basis of myotilinopathies and revealed several motifs in Ig domains found also in I-band proteins." (PMID 28638118, 2017). "The ratio of myotilin to filamin C in aggregate samples was identified as a highly sensitive and specific marker for myotilinopathy." (PMID 26842778, 2016).
muscular dystrophy (7 papers, 2013 to 2024). Muscular dystrophy (MD) refers to a group of more than 30 genetic diseases characterized by progressive weakness and degeneration of the skeletal muscles that control movement. "Mutations in the MYOT gene have been identified as causative factors for muscular dystrophy and other related disorders." (PMID 38585635, 2024). "R405 is mutated in muscular dystrophy and was suggested to be responsible for defective homodimerization of myotilin." (PMID 33844684, 2021). "In summary, this study demonstrates that SNUPN variants are related to a new type of muscular dystrophy with variable phenotypes characterized by contractures, proximal weakness, respiratory involvement, p62 and myotilin aggregates and Z-disc disorganization in histopathology." (PMID 38366623, 2024). "Mutations in the MYOT gene cause various forms of muscular dystrophy." (PMID 23741331, 2013). "MYOT belongs to a small protein family of immunoglobulin (Ig) domain‐containing proteins in the Z‐line associated with the actin cytoskeleton, where MYOT is usually expressed in the heart and involved in muscular dystrophy." (PMID 37395176, 2023).
desminopathies (4 papers, 2013 to 2019). "Out of this long list, stains for αB-crystallin, filamin-C, and myotilin are sensitive diagnostic tools to depict pathological protein aggregation in desminopathies and other forms of MFM." (PMID 23143191, 2013).
distal myopathy (4 papers, 2011 to 2024). Distal myopathy refers to a group of muscle diseases which share the clinical pattern of predominant weakness and atrophy beginning in the feet and/or hands. "This included also a patient with MYOT-associated distal myopathy overseen in the neuromuscular research centre in Halle." (PMID 32361838, 2020). "Based on the available literature, a frequent affection of gluteal muscles was observed in MYOT- associated distal myopathy." (PMID 32361838, 2020). "Muscular involution of the paraspinal musculature was again solely reported in MYOT-associated distal myopathy." (PMID 32361838, 2020). "On the basis of the available literature, patterns of gluteal and paraspinal affection found in MYOT-associated distal myopathy were divergent to the findings in MATR3-myopathy." (PMID 32361838, 2020). "For instance, KLHL9- and ADSSL1-associated distal myopathies are reported to have a rather early onset between 10 and 20 years of age, while first symptoms in MYOT-associated distal myopathy are occurring between 50 and 60 years of age." (PMID 32361838, 2020). "In contrast, relevant similarities were observed in 6 distal myopathies (TIA1, late-stage TTN, MYOT, SQSTM1/TIA1, KLHL9, ADSSL1)." (PMID 32361838, 2020). "MYOT-myopathy usually presents with a myofibrillar histopathology, that has not been identified in MATR3-associated distal myopathy." (PMID 32361838, 2020). "Furthermore, respective changes were not present in MR-studies from patients with MYOT- and SQSTM1/TIA1-associated distal myopathy overseen in the neuromuscular research centre in Halle." (PMID 32361838, 2020).
cardiomyopathy (3 papers, 2021 to 2025). A disease of the heart muscle or myocardium proper. "The MYOT variant has been described in a case of cardiomyopathy with low ejection fraction; other patients displayed left bundle branch block or congestive heart failure." (PMID 38742935, 2024). "For instance, the MYOT p.Ser60Phe variant has been described in a case of myopathy with low ejection fraction and cardiomyopathy, while other patients carrying the variant displayed with cardiomyopathy, left bundle branch block and congestive heart failure." (PMID 33802723, 2021). "Variants in the MYOT gene that have been previously reported in individuals with myopathy or cardiomyopathy." (PMID 33802723, 2021). "This review will focus on six key Z-disc proteins: α-actinin 2, filamin C, myopalladin, myotilin, telethonin and Z-disc alternatively spliced PDZ-motif (ZASP), which have all been linked to myopathies and cardiomyopathies." (PMID 33802723, 2021). "Despite this, no isolated cardiomyopathy cases have been attributed to variants in MYOT." (PMID 33802723, 2021).
heart failure (2 papers, 2014 to 2022). Inability of the heart to pump blood at an adequate rate to meet tissue metabolic requirements. "Patient F9.1 carrying the Ser60Phe mutation in MYOT developed exertional dyspnoea due to heart failure at the age of 64 years as the first symptom." (PMID 25208129, 2014).
Becker muscular dystrophies (1 paper, 2025). "In particular, Pleckstrin (Plek) has been identified as a hub gene in Duchenne and Becker muscular dystrophies, and mutations in Myotilin (Myot) are associated with muscular dystrophy." (PMID 40724839, 2025).
idiopathic dilated cardiomyopathy (1 paper, 2025). Decreased function of the heart associated with cardiac enlargement and congestive heart failure, of unknown cause. "For Idiopathic Dilated Cardiomyopathy (IDC), MNS1 and MYOT intersected between RFE and DEA and had high AUC." (PMID 40287491, 2025).
limb-girdle muscular dystrophy (1 paper, 2024). Limb-girdle muscular dystrophy (LGMD) is a heterogeneous group of muscular dystrophies characterized by proximal weakness affecting the pelvic and shoulder girdles. "Limb-girdle muscular dystrophy (LGMD) is a progressive muscle weakness affecting the pelvic and shoulder girdles, primarily caused by mutations in proteins like myotilin, lamin, caveolin-3, calpain-3, dysferlin, γ-sarcoglycan, TCAP, TRIM32, FKRP, and titin." (PMID 39415830, 2024).
myositis (1 paper, 2025). "Recent proteomic and transcriptomic profiling of anti-Ku myositis identified marked activation of autophagy, proteasome, and hnRNP-linked stress pathways, together with sarcoplasmic aggregates containing p62, BAG3, myotilin and immunoproteasome β5i." (PMID 40599787, 2025).
neuropathy (1 paper, 2018). A disorder affecting the nervous system that manifests with pain, tingling, numbness, and/or muscle weakness. "Three of these now have a confirmed genetic diagnosis (MYH7 and TTN genes in the neuropathy group and MYOT in the IBM group)." (PMID 29997562, 2018).
ovarian carcinoma (1 paper, 2018). A malignant neoplasm originating from the surface ovarian epithelium. "Since we previously observed that COL3A1, LUM and MYOT (under review) are secreted to cell culture media in drug resistant ovarian cancer cell lines, we were interested whether MGP can also be present in the culture medium." (PMID 30257426, 2018).
polyneuropathy (1 paper, 2014). A disease or disorder affecting more than one nerve. "Interestingly, we detected a polyneuropathy in more than a quarter of the MFM patients, including a BAG3 and a MYOT case." (PMID 25208129, 2014).
myopathy (26 papers, 2009 to 2025). A disease of the muscle in which the muscle fibers do not function properly. "Here, we show that duplication of the whole MYOT gene leads to increased expression and aggregation of MYOT causing late‐onset myopathy." (PMID 39757377, 2025). "Its expression is more substantial in skeletal muscles, and myotilin variants are known to cause severe forms of myopathies in humans." (PMID 38742935, 2024). "It thus appears that ZAKβ signalling is required for the turnover of certain proteins and those identified here, FLNC, BAG3 and Myotilin, are implicated in myofibrillar myopathies." (PMID 37427997, 2023). "LDB3 interactors filamin C and myotilin are also expressed in the spinal motor neuron, nerve, and neuromuscular junction, thereby providing the basis for neurogenic manifestations in myopathies associated with mutations in these so-called muscle proteins." (PMID 36609526, 2023). "With respect to myofibrillar myopathy-associated proteins, alpha-crystallin B, desmin, myotilin, BAG family molecular chaperone regulator 3, and heat shock protein beta-8 showed enhanced expression in type I and type IIa fibers." (PMID 34201234, 2021). "MYOT variants mainly manifest in myopathies such as LGMD, MFM, distal myopathy and spheroid-body myopathy." (PMID 33802723, 2021). "Using our template we correctly identified all three MYOT-associated myopathies, which is also one of the best described in the literature." (PMID 29997562, 2018). "For all diseases only one or two articles were available, except MYOT-associated myopathy where there were three." (PMID 29997562, 2018). "In the context of myofibrillar myopathies, mitochondrial pathology has been reported in patients with mutations in filamin-C, myotilin, ZASP, FHL1, plectin, and desmin." (PMID 27393313, 2016). "Mutation in MYOT causes MFM3; this type is defined by the accumulation of products coming from myofibril disintegration with characteristic myofibrillar myopathy symptoms, as this protein plays an important role in sarcomere assembly, interacting with filamin C and a-actinin." (PMID 40869293, 2025). "Missense variants in the MYOT human gene can cause myopathy by accumulating protein aggregates." (PMID 38742935, 2024). "The proteins most frequently described include: proteins more commonly associated with neurodegenerative diseases, namely β-amyloid, phosphorylated tau, and ubiquitin; the myofibrillar-myopathy-associated proteins myotilin and αB-crystallin; and the newer neurodegenerative markers p62 and TDP-43." (PMID 25399751, 2014). "On muscle biopsy, typical myofibrillar myopathy changes are seen, including rimmed vacuoles and aggregates reactive for myotilin, αB-crystallin, dystrophin, HSPB8, DNAJB6, myotilin, BAG3, TDP43 and ubiquitin." (PMID 39501809, 2024). "We also confirmed the presence of myotilin, another myofibrillar myopathy marker, in the FLNC-positive fibres." (PMID 37427997, 2023). "Furthermore, BAG3 mutations can cause myofibrillar myopathies and cardiomyopathy, in which accumulation of BAG3 or myofibrillar proteins, e.g., myotilin, desmin, and αB-crystallin, can be found." (PMID 39012547, 2024). "Interestingly, BAG3 or αB-crystallin aggregation as well as aggregation of myofibrillar structural proteins like myotilin and desmin in the Ku + biopsies resemble aggregation in myofibrillar myopathies." (PMID 39012547, 2024). "In addition to LDB3, other rare myopathy gene products such as filamin C and myotilin are expressed in the nervous system [this study; (Mologni13; Xie14)]." (PMID 36609526, 2023). "We may first establish the relationship between MYOT and autophagy, which may provide news perspectives between MYOT and myofibrillar myopathies." (PMID 36776921, 2023). "In addition, resemblance to other myofibrillar myopathies was observed as myotilin-positive myofibrillar lesions also contain BAG3 and HSPB8." (PMID 33974137, 2021).